OLR1 (oxidized low density lipoprotein receptor 1)
Diseases named in the same sentence as OLR1 in open-access papers (continued):
Sharing a sentence is not in itself a finding about the gene and the disease.
colon carcinoma (continued). "The results showed that OLR1 expression was positively correlated with c-MYC in colon cancer, indicting OLR1 might promote c-MYC expression in colon cancer." (PMID 34921134, 2021). "The results suggested that OLR1 might be involved in the occurrence and development of colon cancer." (PMID 34921134, 2021). "Hence, this research was designed to explore the mechanism underlying the OLR1/c-MYC/SULT2B1 axis in the regulation of glycolytic metabolism, to affect colon cancer cell proliferation and chemoresistance." (PMID 34921134, 2021). "Here, we propose that OLR1 may participate in glycolytic metabolism, proliferation, and chemoresistance of colon cancer cells." (PMID 34921134, 2021). "Moreover, ectopic expression of OLR1 has been noted to augment colon cancer onset, progression, and metastasis." (PMID 34921134, 2021). "Generally speaking, knockdown of OLR1 might inhibit the tumorigenicity and chemoresistance of colon cancer cells in nude mice by downregulating c-MYC and SULT2B1." (PMID 34921134, 2021). "Collectively, knockdown of OLR1 could inhibit the proliferation and chemoresistance of colon cancer cells via c-MYC downregulation." (PMID 34921134, 2021). "Moreover, OLR1 was highly expressed in colon cancer in these three datasets." (PMID 34921134, 2021). "Furthermore, another study has reported that SULT2B1 is highly expressed in chemoresistance colon cancer and radio-resistance tissues, which promotes cell proliferation and chemoresistance in colon cancer through its involvement in oncogenic signaling involving the OLR1/c-MYC/SULT2B1 axis." (PMID 39280099, 2024). "In order to further determine the relationship between OLR1 and c-MYC in colon cancer, the expression data of OLR1 and c-MYC in GSE10950, GSE41328, and GSE75970 were normalized, respectively." (PMID 34921134, 2021). "All in all, knockdown of OLR1 might downregulate SULT2B1 to repress glycolytic metabolism, thereby dampening the proliferation and chemoresistance of colon cancer cells." (PMID 34921134, 2021). "The results documented that the sensitivity of LoVo colon cancer cells to DDP, oxaliplatin, 5-Fu, and paclitaxel was obviously increased, P-gp expression was significantly decreased, and SMAD4 expression was clearly enhanced after knocking down OLR1." (PMID 34921134, 2021). "The levels of OLR1, c-MYC, and SULT2B1 were upregulated in colon cancer tissues and cells." (PMID 34921134, 2021). "Moreover, knockdown of OLR1, c-MYC, or SULT2B1 weakened glycolytic metabolism, proliferation, and chemoresistance of colon cancer cells." (PMID 34921134, 2021). "In order to further explore whether OLR1/c-MYC/SULT2B1 axis could also modulate the growth and chemoresistance of colon cancer cells in vivo, a subcutaneous tumor transplantation experiment was implemented in nude mice." (PMID 34921134, 2021). "Conclusively, knockdown of OLR1 might diminish SULT2B1 expression by downregulating c-MYC, thereby restraining glycolytic metabolism to inhibit colon cancer cell proliferation and chemoresistance." (PMID 34921134, 2021). "In conclusion, high expression of c-MYC in colon cancer tissues and cells was observed, and knockdown of OLR1 could downregulate c-MYC and repress the proliferation and chemoresistance of colon cancer cells." (PMID 34921134, 2021). "Furthermore, the sensitivity of LoVo colon cancer cells to DDP, oxaliplatin, 5-Fu, and paclitaxel was distinctly enhanced, P-gp expression was authentically declined, and SMAD4 expression was noticeably augmented subsequent to OLR1 knockdown, which was reversed by further overexpressing c-MYC." (PMID 34921134, 2021). "It suggests that the hsa-mir-21-5p to COL5A2/OLR1, hsa-mir-135b-5p/hsa-mir-495-3p/hsa-mir-409-3p to COL5A2 and hsa-mir-224-5p/hsa-mir-21-3p/hsa-mir-135b-5p/hsa-mir-495-3p to EDNRA pathways may play substantial roles in regulation of the tumor immune microenvironment in colon cancer." (PMID 31500382, 2019).
COVID-19 (19 papers, 2021 to 2025). A disease caused by infection with severe acute respiratory syndrome coronavirus 2. "A significant increase of low-density neutrophils (LDNs) expressing lectin-type oxidized low-density lipoprotein receptor 1 (LOX-1) in the blood of patients with acute COVID-19 was also observed." (PMID 35572540, 2022). "The top molecules in the COVID-19 T1 and T2 data set with the greatest alteration in methylation compared to healthy controls included hypomethylated MUC20, VAV3, CCL20, and mir21 and hypermethylated GIT2, IFNGR2, FCER1G, and OLR1." (PMID 41227320, 2025). "Given that the influenza-associated lung thrombosis did not occur in Olr1 knockout mice, it is possible that LOX-1 is also involved in promoting the thrombus formation in COVID-19." (PMID 34834944, 2021).
pancreatic cancer (19 papers, 2018 to 2025). "The OLR1 gene mainly encodes a low-density lipoprotein receptor, and it has been shown that OLR1 promotes pancreatic cancer metastasis by increasing c-Myc expression and HMGA2 transcription." (PMID 36579330, 2022). "Consistently, OLR1 upregulation was observed in pancreatic cancer tissues and was associated with the poor prognosis of patients, and then OLR1 abrogation caused resistance of pancreatic cancer cells to gemcitabine." (PMID 34921134, 2021). "We will construct pancreatic cancer liver metastases models in mice using SLC7A7 and OLR1 knockout pancreatic cancer cells to verify their crucial roles in pancreatic cancer liver metastases." (PMID 41176774, 2025). "It has been reported that OLR1 promotes pancreatic cancer metastasis via increased c-Myc expression and transcription of HMGA2." (PMID 35154316, 2022). "In gemcitabine-resistant cells, GSTM3TV2 promoted the drug resistance by sponging let-7 for upregulating L-type amino acid transporter 2 (LAT2) and oxidized low-density lipoprotein receptor 1 (OLR1) in pancreatic cancer cells." (PMID 34745970, 2021). "More importantly, OLR1 is also reported to be positively correlated with the occurrence of lymphatic metastases in pancreatic cancers." (PMID 34900686, 2021). "The outcome was the regulation of c-Myc and HMGA2 expression exerted by OLR1 in order to promote pancreatic cancer metastasis." (PMID 33402733, 2021). "Binding with miR-let-7 in the cell cytoplasm, lncRNA GSTM3TV2 served as a ceRNA to up-regulate LAT2 and OLR1 expression, promoting cell gemcitabine resistance in pancreatic cancer." (PMID 33442418, 2021). "As previously documented, OLR1 triggered c-MYC upregulation to accelerate pancreatic cancer metastasis." (PMID 34921134, 2021). "We observed that LAT2 and OLR1 were upregulated in gemcitabine-resistant pancreatic cell lines and that inhibiting their expression enhanced the chemosensitivity of pancreatic cancer cells to gemcitabine." (PMID 31514732, 2019). "The results showed that OLR1 and SLC7A7 were highly expressed in pancreatic cancer patients and associated with the disease stage, indicating that OLR1 and SLC7A7 were important for the diagnosis of pancreatic cancer." (PMID 41176774, 2025). "In pancreatic cancer, OLR1 promotes metastasis through c-MYC and HMGA2." (PMID 37629087, 2023). "Consistently, LAT2 and OLR1 were direct targets of let-7 families, and GSTM3TV2 could upregulate the expression of LAT2/OLR1 in pancreatic cancer cells via competitively sponging let-7." (PMID 31514732, 2019). "Interestingly, it was illustrated in another research that OLR1 upregulation could enhance c-MYC expression to accelerate pancreatic cancer metastasis." (PMID 34921134, 2021). "Next, to validate whether GSTM3TV2 modulated LAT2 and OLR1 to promote chemoresistance in pancreatic cancer, we constructed the specific siRNAs targeting LAT2 and OLR1 (siLAT2 and siOLR1, respectively) to silence the expression of LAT2 and OLR1 in MIAPaCa-2/GR and Rv-AsPC-1-GSTM3TV2 cells." (PMID 31514732, 2019). "The marker genes OLR1 and SLC7A7, which were significantly upregulated in LEMS, were validated in clinical samples, suggesting their potential as biomarkers for pancreatic cancer liver metastases." (PMID 41176774, 2025). "Further studies are needed to investigate the correlation of OLR1 and SLC7A7 with pathological staging and survival in pancreatic cancer patients through immunohistochemistry." (PMID 41176774, 2025). "OLR1 has been demonstrated to participate in modulation of the EMT process, thereby instigating the metastasis of pancreatic cancer and osteosarcomas." (PMID 37629087, 2023). "This lncRNA is able to promote gemcitabine-resistance in pancreatic cancer cells through a mechanism of upregulation of both LAT2 (Linker for activation of T-cells family member 2) and OLR1." (PMID 33402733, 2021).
pancreatic cancer (continued). "We found that GSTM3TV2 promoted pancreatic cancer gemcitabine resistance by upregulating LAT2 and OLR1 though competitively sponging let-7." (PMID 31514732, 2019). "However, there are very few reports on the roles of OLR1 and SLC7A7 in pancreatic cancer liver metastases." (PMID 41176774, 2025). "Furthermore, we analyzed the expression levels of OLR1 and SLC7A7 in pancreatic cancer patients using the GPEIA2." (PMID 41176774, 2025). "Thus, all these results confirmed the critical role of GSTM3TV2 in gemcitabine resistance of pancreatic cancer cells via LAT2 and OLR1." (PMID 31514732, 2019). "We then investigated that GSTM3TV2 could promote pancreatic cancer gemcitabine resistance by upregulating L-type amino acid transporter 2 (LAT2) and oxidized low-density lipoprotein receptor 1(OLR1) though competitively sponging let-7." (PMID 31514732, 2019).
prostate carcinoma (18 papers, 2014 to 2023). A carcinoma that arises from epithelial cells of the prostate gland. "The C4-2 prostate cancer cell lines were transduced with the lentiviral expression vector LvCW-LOX-1, encoding the olr1 gene under the control of the cytomegalovirus promoter (CMVP), and isolated using the limiting dilution cloning method." (PMID 25170920, 2014). "Prostate cancer progression has been linked to high-level expression of lipid metabolism genes (e.g., OLR1, GLRX and SNAP23) which could contribute to the dysregulation of lipid distribution in the tumor cell membrane." (PMID 35631014, 2022). "Moreover, other studies placed the aim to clarify the role of OLR1 in prostate cancer." (PMID 33402733, 2021).
colorectal cancer (17 papers, 2012 to 2026). A primary or metastatic malignant neoplasm that affects the colon or rectum. "The gene encoding oxidized low-density lipoprotein receptor 1 (OLR1), a human granulocyte Neut/MDSC-specific marker was significantly elevated in all molecular subtypes of colorectal cancer, with highest expression in CMS1 and CMS4." (PMID 36911097, 2023). "Finally, based on a median low verses high gene expression split, high CSF3, MPO, and OLR1 gene expression was associated with reduced disease-specific survival (CSF3 and MPO) and overall survival (ORL1) in colorectal cancer." (PMID 36911097, 2023).
ischemic stroke (15 papers, 2015 to 2025). A stroke disorder caused by obstruction of blood flow to the brain, due to thrombotic (local blood clot formation) or embolic (due to a blood clot or other material traveling from another site) event. "Pooled results from the genetic models indicated that OLR1 rs11053646 dominant (OR = 1.33, 95% CI:1.11–1.58) and co-dominant models (OR = 1.24, 95% CI:1.02–1.51) were significantly associated with ischemic stroke." (PMID 26666837, 2015). "In this meta-analysis, OLR1 rs11053646 C allele is associated with ischemic stroke in the dominant model and/or in the recessive model." (PMID 26666837, 2015). "The overall prevalence of PCSK9 rs505151 and OLR1 rs11053646 variants in ischemic stroke were 0.005 and 0.116, respectively." (PMID 26666837, 2015). "Nevertheless, the dominant model of OLR1 rs11053646 was significantly increased the risks towards ischemic stroke with odd ratio (OR) 1.33 (95% CI:1.11–1.58, p = 0.002)." (PMID 26666837, 2015). "Thus far, no meta-analysis has yet been conducted to investigate the relationship between OLR1 rs11053646 and PCSK9 rs505151 polymorphisms and ischemic stroke." (PMID 26666837, 2015). "In conclusion, the current meta-analysis highlighted that variant allele of OLR1 rs11053646 G > C and PCSK9 rs505151 A > G may contribute to the susceptibility risk of ischemic stroke." (PMID 26666837, 2015). "In conclusion, the current meta-analysis suggested that the variant alleles of OLR1 rs11053646 and PCSK9 rs505151 may confer an increased risk of ischemic stroke." (PMID 26666837, 2015). "Interestingly, both of the co-dominant models for OLR1 rs11053646 and PCSK9 rs505151 demonstrated similar odds towards ischemic stroke (OR = 1.24, 95% CI:1.02–1.51, p = 0.03; OR = 1.36, 95% CI:1.01–1.85, p < 0.05, respectively)." (PMID 26666837, 2015).
type 2 diabetes (13 papers, 2011 to 2025). "Whole blood OLR1 mRNA levels were significantly decreased by 37% after bariatric surgery in our study, consistent with a previous study reporting that the serum levels of the sLOX1 protein is higher in type 2 diabetes patients than in controls." (PMID 21423737, 2011). "Since high glucose can upregulate ADAM10 expression in vitro, we investigated whether serum levels of ADAM10 and its substrate, the lectin‐like oxidized low‐density lipoprotein receptor 1 (LOX‐1), can be influenced by type 2 diabetes." (PMID 35705192, 2022).
heart failure (10 papers, 2016 to 2025). Inability of the heart to pump blood at an adequate rate to meet tissue metabolic requirements. "In addition, the expression levels of CXCL11 and OLR1 have been proved to be elevated in heart failure patients." (PMID 37268658, 2023).
Sepsis (10 papers, 2010 to 2025). Sepsis is defined as life-threatening organ dysfunction caused by a dysregulated host response to infection. "GSEA highlighted enrichment in “innate immune system”, “lung olr1 classical monocyte cell” and “positive regulation of protein metabolic process” pathways in sepsis, and the “innate immune response” pathway in AF." (PMID 39444551, 2024). "For example, lectin-like oxidized low density lipoprotein receptor-1 (LOX-1), has been shown to mitigate sepsis-induced lung injury in models where it is systemically inhibited, but its contribution to the local response in the lung is not yet known." (PMID 36829255, 2023). "Lox-1 (OLR1), a typical G-MDSC gene, was highly expressed but varied considerably within MBC and sepsis samples." (PMID 32958605, 2020).
Hypercholesterolemia (9 papers, 2013 to 2024). An increased concentration of cholesterol in the blood. "The importance of the link between LOX-1 and statins in arterial disease is further highlighted in a cohort study of 751 patients with hypercholesterolaemia receiving statin therapy: OLR1 (LOX-1) polymorphisms are linked to circulating LDL levels and risk of CVD." (PMID 33182772, 2020).
psoriasis (9 papers, 2010 to 2025). An autoimmune condition characterized by red, well-delineated plaques with silvery scales that are usually on the extensor surfaces and scalp. "In psoriasis, CCL4, GZMK and KLRF1 show significantly higher, while ADM, ANXA3, IL4, MMP9 and OLR1 show significantly lower expression levels in patients with arthritis negative psoriasis compared to patients with symptoms of arthritis." (PMID 20444268, 2010).
osteosarcoma (8 papers, 2019 to 2023). A usually aggressive malignant bone-forming mesenchymal neoplasm, predominantly affecting adolescents and young adults. "Compared with high expression, low expression of OLR1 was associated with higher OS for patients with osteosarcoma." (PMID 31718700, 2019). "Moreover, high OLR1 expression in primary human osteosarcoma samples was associated with poor prognoses." (PMID 31718700, 2019). "Integrally, the present findings illustrated a novel step forward in comprehending the effect of gene OLR1 in osteosarcoma metastases and provided a potential target for targeted osteosarcoma therapy." (PMID 31718700, 2019). "The current observation provided a potential opportunity in osteosarcoma targeted therapy involved in OLR1 gene." (PMID 31718700, 2019). "This study indicated a novel molecular mechanism involving the role of OLR1 in osteosarcoma metastases, strengthened the correlation between OLR1 and osteosarcoma progression, and examined the role of OLR1 in EMT." (PMID 31718700, 2019). "In the present study, we identified OLR1 as a highly-overexpressed protein in osteosarcomas that seemed critically involved in the malignant behavior of this disease, presumably, in part, via the EMT approach." (PMID 31718700, 2019). "The silencing of OLR1 inhibited osteosarcoma cell invasion and migration in vitro, as well as lung metastasis in mice in vivo." (PMID 31718700, 2019). "In this study, novel insights involved in the OLR1 function and its role in osteosarcoma metastases were gained." (PMID 31718700, 2019). "This study indicated a novel molecular mechanism involving the role of OLR1 in lung metastases of osteosarcoma, strengthened the correlation between OLR1 and lung metastases." (PMID 31718700, 2019). "Besides, a prior study noted that OLR1 presented with high-expression in osteosarcoma tissues and that osteosarcoma cell proliferation was accelerated when OLR1 was ectopically expressed." (PMID 34921134, 2021). "The silencing of OLR1 expression in osteosarcoma cell lines resulted in suppression of metastases." (PMID 31718700, 2019). "On the basis of this phenomenon, our hypothesis was that OLR1 was involved in osteosarcoma metastatic potential." (PMID 31718700, 2019). "The hypothesis was that the metastasis of osteosarcoma might, at least in part, be due to high or present OLR1 expression." (PMID 31718700, 2019). "Furthermore, we showed that OLR1 is also important for colony formation and proliferation of osteosarcoma cells in vitro and for tumorigenicity and metastases in vivo." (PMID 31718700, 2019). "Furthermore, the promotive effect of OLR1 in osteosarcoma cell migration and lung metastasis was mediated by EMT." (PMID 31718700, 2019). "In the current study, we show that OLR1 could promote metastases of osteosarcoma in vitro and in vivo." (PMID 31718700, 2019). "In this study, OLR1 expression was analyzed in osteosarcoma cell lines and human samples." (PMID 31718700, 2019). "OLR1 could also promote lung metastases of osteosarcomas through regulating the EMT." (PMID 38022584, 2023). "Silencing OLR1 gene in vitro in two OS cell lines (143b and MG63) overexpressing LOX-1, allows to inhibit osteosarcoma cell invasion and migration and to prevent in vivo metastasis formation." (PMID 33402733, 2021). "The current study firstly provided evidence that OLR1 regulated EMT and thus promoted lung metastasis in osteosarcoma." (PMID 31718700, 2019). "Here, we described that OLR1 induced EMT, thus subsequently promoted lung metastases in osteosarcomas." (PMID 31718700, 2019). "The current study firstly provided evidence that OLR1 regulated EMT and thus promoted lung metastases in osteosarcoma (OS)." (PMID 31718700, 2019).
rheumatoid arthritis (8 papers, 2010 to 2024). A chronic, systemic autoimmune disorder characterized by inflammation in the synovial membranes and articular surfaces. "In serum samples from SLE patients, it has been reported overexpression of Pglyrp1, a member of the family of bacterial peptidoglycan sensor molecules, and also it was associated with other autoimmune diseases like rheumatoid arthritis Besides, SLE severity is associated with Olr1." (PMID 35211864, 2022).
lymph node metastasis (6 papers, 2017 to 2022). "High levels of OLR1 expression are associated with more aggressive and metastatic stage, like stages III and IV, and lymph node metastasis." (PMID 33402733, 2021).